CD44 (CD44 molecule (IN blood group))
Diseases named in the same sentence as CD44 in open-access papers (continued):
Sharing a sentence is not in itself a finding about the gene and the disease.
tumor (continued). "The immune cell profile of immunized mice had a significantly higher number of activated T cells, as indicated by the increased frequency of CD44+CD4+ and CD44+CD8+ T cells, which have a crucial role in suppressing tumor growth, as compared to the untreated controls." (PMID 39534596, 2024). "To examine whether our induced tumor-CAF spheres exhibit CSC properties, we further assessed the expression of CD44 and CD133 within the co-cultured spheres, MIA PaCa-2 + CAF and Capan1+ CAF." (PMID 38495500, 2024). "In contrast, the elevated levels of CD44 in tumor cells and in stroma in NSGCTs are not related to any clinicopathological variable." (PMID 38796656, 2024). "High CD44 expression in tumors enables selective binding and internalization of CA102N, making CD44-mediated targeting a critical factor for drug targeting and tumor selectivity." (PMID 39703390, 2024). "Tumor-recruited Hyal2+ myeloid cells are activated in the TME to break down HA through the translocation of Hyal2 to the cell membrane, which is dependent on the CD44 signaling pathway." (PMID 38946426, 2024). "Conversely, many genes have broad, often bi-/multimodal distribution (for example CD44, CCND1 and CD74 in tumour and STAT1 in both compartments for all p16/HPV subgroups), potentially reflecting spatial context – tumour core versus tumour periphery or tumour-adjacent versus more distant stroma." (PMID 39328208, 2024). "Additionally, MIF released from DKK1+ tumor cells activated CD74, CXCR4, and CD44 on immune clusters." (PMID 39505867, 2024). "In addition, OPN directly suppresses the anti-tumor functions of CD8+ T cells by binding to its receptor CD44 in T cells, suggesting OPN as a multifunctional immunosuppressant in the tumor microenvironment." (PMID 38416830, 2024). "The hyaluronan receptor CD44, which has also been proposed as a SLGC and GBM subtype marker with significance in tumor progression showed varying expression levels in Western blots, in which high CD44 expression was observed for both SLGC cultures with high and low Sox2 levels." (PMID 38306361, 2024). "This beneficial effect occurs through (a) the suppression of stem cell markers (such as CD44) and cell adhesion molecules like uPAR/PAI-1, which are involved in tumor progression and metastasis, (b) the cell cycle inhibition, and (c) the increase in cell death by apoptosis." (PMID 39339789, 2024). "Apart from CD44, HA also interacts with CD44‐like receptors such as HA‐mediated motility receptor (RHAMM) and lymphatic vessel endothelial receptor‐1 (LYVE‐1), which are also overexpressed in tumor cells." (PMID 39217459, 2024). "Furthermore, we performed immunohistochemistry (IHC) of the representative signatures (CD44 and GZMK) of the CD8+ Tem49 to evaluate tumor infiltration in tissue samples from therapy-naïve CRC patients." (PMID 38302471, 2024). "In addition, the expression levels of CD163, CD68, CD44, and CD133 in GBC tissues were significantly correlated with tumor metastasis." (PMID 39138521, 2024). "Consistently, UA treatment not only led to decreased apoptosis and increased proliferation of transferred CTLs in the tumor, spleen, and lymph node of recipient mice but also dramatically increased the proportion of CTLs with a CD62L+CD44+ TCM phenotype." (PMID 38447147, 2024). "Further studies evaluating the biochemical pathways CD44 and ALDH1A1 in OS compared to other cancers may further elucidate critical differences that affect tumor behavior." (PMID 38371078, 2024). "For the first time, it was reported that RT can exert a direct and discernible influence on CD-44 expression, with a dose-dependent increase observed specifically in the tumour cell line, as opposed to the healthy line." (PMID 38172135, 2024). "In the control-treated tumor, CAFs in all 3 clusters appeared to be the main source of the growth factor ligands including TGF-βs, FGFs, and VEGFs, which bind to the receptors including CD44, TGF-βRs, and ITGs." (PMID 39298276, 2024).
tumor (continued). "Tumor TIF proteins with pI below 5.5, including CD44 and OPN, were easily to be adsorbed on CP1-LVs with high amino/hydroxyl ratio, promoting nanovesicle internalization in tumor cells through CD44- and OPN-mediated pathways." (PMID 38326312, 2024). "In our study, initial findings revealed elevated CD44 staining in metastatic sites compared to primary tumours, although multivariate analysis did not reveal a significant association with poor prognosis." (PMID 38719848, 2024). "Thus, we conducted quantitative assessments of the immunoexpression levels of CSC markers, including ALDH1, CD44, p75NTR, and BMI-1, along with E-cadherin, in both OSCC primary tumours and metastatic lymph nodes through the utilization of IHC." (PMID 38719848, 2024). "CD44 is a complex transmembrane adhesion glycoprotein recognized as a marker of cancer stem cells and a key regulator of epithelial-mesenchymal transition (EMT), involved in tumor initiation, progression, and metastasis." (PMID 39143438, 2024). "CD44 is also involved in the epithelial-mesenchymal-transition (EMT) process and in extravasation through the endothelial barrier, both of which stimulate tumor invasion and metastasis." (PMID 39430073, 2024). "However, tumor-infiltrating CD8+ Tex cells in trained mice displayed a higher expression of Ki67, CD44, and CD103, indicating that trained condition was associated with a functional and proliferative reinvigoration on CD8+ Tex cells." (PMID 38812523, 2024). "To assess anti-tumor memory, we measured splenic CD8+CD44+CD62L− effector memory T cells (CD8+ Tems) that could elicit immediate protections by producing cytokines." (PMID 38553476, 2024). "During observation, no changes in tumor volumes of control and CD44 knockdown cell lines before radiation exposure were detected." (PMID 39132508, 2024). "This was attributed to the fact that CP1-LVs adsorbed a large number of tumor stromal proteins, including OPN and CD44, which could increase the internalization efficiency of nanovesicles into tumor cells." (PMID 38326312, 2024). "For example, inhibition of the interaction of cancer cells with pericytes by suppressing CD44 and CDC42 could induce cancer cells to develop another tumor growth pattern and has enhanced the anti-tumor immune response." (PMID 38255995, 2024). "Given the described role of FAP+ CAFs in regulating desmoplastic reaction and CD44+ macrophages as highly phagocytic cells, in an attempt to speculate these cells can cooperate to a ECM remodeling niche that promotes tumor cell invasion and PDAC progression." (PMID 39575252, 2024). "In agreement with the hypothesis that tumor-intrinsic IFNγ signaling is required for antitumor immunity, Ifngr2−/− KPAR tumors had less central memory (CD62L+CD44+) CD8+ T cells, which are important for durable antitumor immune responses." (PMID 38635884, 2024). "Importantly, in tumor, mHAdLyp.sT treatment also increased the percentage of CD8+ central memory cells (TCM, CD44+CD62L+) significantly on day 14 (P < 0.05 vs buffer)." (PMID 38267626, 2024). "Moreover, CD44, CXCL12 and TGFBR2 were positively correlated with all tumor infiltrating immune cells." (PMID 38877052, 2024). "Although CD44 is responsible for promoting various physiological functions such as cellular adhesion as well as communication between cells and the ECM, its aberrant overexpression gives rise to pathological occurrences such as tumour progression." (PMID 38816670, 2024). "Tumor cells (n=38284; 31.2%, n=8; range 22.5-37.2% per PDAC) were annotated into 7 different subtypes, based on the expression of Pan-Ck, cytokeratin 7 (Ck-7), CD44, S100A4, PTX3, CA-IX, CD74." (PMID 39575252, 2024). "MIF released from MMP7+ tumour cells activated CD74, CXCR4 and CD44 on immune clusters." (PMID 39187937, 2024). "However, CD27+Ly6C− and CD27+Ly6C+ γδ T cells within the tumor microenvironment expressed the same levels of CD160, NKG2A, NKp46, and CD44, with NKG2A expression in KP tumors being an exception." (PMID 38816652, 2024).
tumor (continued). "As nanomedicine reaches at tumor site via EPR, the nanomedicine could be taken by cancer cell specifically owing to its high CD44 expression on the surface of cancer cell." (PMID 39479443, 2024). "CD44 is a non-kinase cell surface transmembrane glycoprotein that has been shown to play an important role in malignant transformation and tumor progression." (PMID 38736877, 2024). "Furthermore, EVs from tumor cells of patients with cachexia and hepatocellular carcinoma carrying CTLA-4 have been shown to promote tumor cell proliferation and metastasis through the PTEN/CD44 pathway within the tumor microenvironment." (PMID 39528800, 2024). "Notably, these markers have previously been linked to different cell types, including endothelial cells (CD44, ENG, F3, MCAM, and ITGB1), immune cells (CD14, CD44, CSPG4, ENG, HLA-DR/DP/DQ), and neuronal cells (NCAM1), as well as astrocytes and tumor cells." (PMID 39594703, 2024). "In addition, monocytes/macrophages and CD8+ T cells at the tumor margin expressed higher levels of MHC–II and CD44, respectively, reflecting a different state of inflammatory activation of these cells." (PMID 38338669, 2024). "Indeed, in MC38-luc-tumor-bearing mice, combined CD44- and CD25-targeted NIR-PIT significantly reduced tumor size and regrowth following treatment." (PMID 38612911, 2024). "As our previous study showed that VDAC1-tumor depletion eliminated CSCs, the tumors treated with si-NT or with si-m/hVDAC1-B were analyzed for the expression levels of CSC markers CD133 and CD44 in SCLC." (PMID 39272828, 2024). "In comparison to adherent cells, the tumor spheroids thus generated showed an increased expression of stem markers, such as ALDH1A1, CD44, and CD133, and core transcription factors of the human stem cell pluripotency signaling pathway, such as Oct4, Sox2, and Nanog." (PMID 39335624, 2024). "Reintroduction of CD44s into cancer cells restored their tumor growth capacity, suggesting that CD44 is not merely a marker but also plays an essential role in promoting CSC traits." (PMID 39335624, 2024). "CD44, a cell surface protein extensively expressed on lymphocytes and nonlymphoid cells, plays crucial roles in tumor angiogenesis, lymphocyte homing, activation, and proliferation, as well as cell adhesion and migration." (PMID 38721005, 2024). "Notably, our results suggest that CD14+ TAMs significantly enhanced tumor SFE and the proportion of CD133+ CD44+ cells in GBC cells." (PMID 39138521, 2024). "Furthermore, LASS2-knockdown pBCs formed more colonies when exposed to cisplatin and led to an expansion of CD44+ALDH1A1+ subpopulation, also enhancing the capability of tumor sphere formation." (PMID 38191448, 2024). "Cell-cell interactions, particularly involving CD44-SPP, were identified between tumor cells." (PMID 39483146, 2024). "The number of tumor microvessels was significantly increased in the paranecrotic areas of CD44 kd tumors (P = 0.0407, unpaired t‐test) but not at the tumor margin." (PMID 37849446, 2024). "Moreover, CQ increased the sensitivity to PTX and reduced lung metastases, tumor growth, and recurrence in orthotopic murine MDAMB231 and SUM159PT tumor models and diminished the CD44+/CD24−/low CSC population in a clinical trial." (PMID 38256019, 2024). "Next, the in vitro experiments revealed that the tsRNA-GlyGCC inhibitor suppresses cell proliferation, migration, and formation of tumor spheres by modulating the protein expression of BCL2, BAX and cancer stem cells molecular markers (CD44,CD133, EphB2, LICAM, and LGR5)." (PMID 39153969, 2024). "CD44 is a non-kinase cell surface transmembrane glycoprotein with a pivotal role in controlling the tumorigenic features of tumor cells." (PMID 39457544, 2024). "HIF‐2α was widely expressed in the vital tumor masses between the tumor margin and necrotic center but was not altered upon CD44 kd." (PMID 37849446, 2024).
tumor (continued). "Additionally, IF examination of tumor sections from both lung tissues and primary tumor tissues indicated GGT1 depletion accompanied by low level of CD44." (PMID 38523299, 2024). "Because IM7 is a pan-CD44 mAb, IM7 might target not only tumor cells but also CD44s-positive immune cells which are involved in the antitumor immunity." (PMID 39273139, 2024). "The congenital deficiency of CD11chi DCs not only reduced the expression of CD44 on CD4+ T cells and CD8+ T cells in lymphoid tissues under homeostatic and tumor-bearing conditions but also enhanced their expressions of several immune checkpoint molecules under tumor-bearing conditions." (PMID 39206204, 2024). "CD44 and CD133 are recognized surface markers of tumor stem cells." (PMID 38706601, 2024). "We identified a negative correlation between tumor cells that were non-stem by CD44/CD24 but stem by CD133 and those that were CD44+CD24−CD133− in EpCAM-negative CTCs (r = −0.69, p = 0.024)." (PMID 39456890, 2024). "The CD44+CD24low/neg population was heterogeneous, however, since further fractionation using epithelial specific antigen provided ~50-fold XIC activity relative to unfractionated tumor cells." (PMID 37832945, 2024). "While TAMs might be involved in the regulation of the α5 integrin, MDSCs-driven production of NO could downregulate the expression of the CD44 and PSGL-1 (CD162), therefore impairing T cell extravasation and tumor infiltration." (PMID 39596815, 2024). "We chose TM4SF1, CD44, CD133, and OCT4 as the primary antibodies to combine with tumor tissues." (PMID 37069693, 2023). "Additionally, the same effects were observed in metastatic ovarian cancer models and were accompanied by the infiltration and accumulation of CD44+ IFNγ-secreting CD8+ and CD4+ T cells at tumour beds." (PMID 38136940, 2023). "As compared to control or ICBs, guadecitabine alone and in combination with ICBs upregulated T cell responses by increasing granzyme production on tumor infiltrating CD8+ T cells, favoring the maturation of CD8+T cells in effector memory (CD44+CD62L-) cells secreting granzyme." (PMID 36934257, 2023). "Aiming at a particular identification of the predominant cell types and the accordingly conveyed tumor-modulating effects, additional staining analyses of the present EOC patient cohort defined the subset of ACTBL2-positive TILs as CD44-expressing cytotoxic T-cells (CD8 +) and macrophages (CD68 +)." (PMID 38114558, 2023). "Analysis of tumour-infiltrating lymphocytes revealed no changes in the expression of memory-associated markers (CD62L and CD44) or exhaustion-associated markers (TIM3, PD1, LAG3, TOX) in CD4+ or CD8+ cells." (PMID 37605057, 2023). "CD44 also facilitates tumor angiogenesis, immunosuppression, and metabolic reprogramming through interactions with STAT3, thereby supporting the pro-tumorigenic tumor microenvironment." (PMID 37284314, 2023). "Moreover, it has been shown that levels of serum TNF-α, IL-2, and serum CD44 (sCD44) are all increased in NHL and correlate with tumor burden, the presence of symptoms, and other clinical and laboratory variables." (PMID 36831345, 2023). "In addition, P/C ratios of CD44 expression in all 21 GBM patients correlated with the strength of 5-ALA fluorescence at final resection, representing the strength of tumor invasiveness." (PMID 37760811, 2023). "The flow cytometry results showed that RT-MPs significantly decreased the percentage of CD44-positive tumor cells, while DDP did not." (PMID 37342505, 2023). "Additionally, we studied the expression of key proteins involved in the EMT process, including E-cadherin and vimentin, and of proteins related to the tumor phenotype, such as ER, PR, ERBB2, Ki-67, cytokeratin (CK) 8/18, CK5/6, CK14, and CD44." (PMID 36899736, 2023).
tumor (continued). "Using anti‐CD44 monoclonal antibody, the levels of phosphorylated‐mTORC1, phosphorylated‐mTORC2 and phosphorylated‐Akt were reduced, leading to enhanced differentiation of HL60, THP‐1 and KG1a leukaemic cells and tumour growth suppression." (PMID 37156724, 2023). "Similar to G411 xenograft tumors, pronounced CD44 expression is present in G361 MSH6−/− tumor cells but not nontumoral cells." (PMID 36989359, 2023). "We sought to explore the specific reasons for the differences in CD44 expression between tumor and non-tumor tissues and to find the subgroup with the greatest differences." (PMID 37316699, 2023). "Consistent with the CD8+ T cell data, the CD44+CD8+ T cells in peripheral tissue did not provide protection against tumor cells in vivo." (PMID 36759517, 2023). "As cancer stem cells are known for their intrinsic resistance to chemotherapy and radiation, it is reasonable to expect that CD44-positive cells (CSCs) exhibit higher resistance to conventional therapies than CD44-negative cells (non-CSCs) within the tumor." (PMID 37958796, 2023). "Lack of Nos2 also decreased the proportion of tumor-specific (OT-I) CD44+ cells circulating in the blood." (PMID 36574610, 2023). "CD44 expression was in turn responsible for the elevation of ECM proteins such as TGFβ and MMP9, which further enhanced the fusion of these endothelial cells with ECM components to promote tumor neovascularization." (PMID 38170015, 2023). "The objective of this study was to evaluate the expression of ZEB1 and its regulation by miRNAs and genes involved in hypoxia and EMT, in addition to evaluating the potential of the two populations of tumor stem cells: ALDH+ and CD44/CD117/133 triple-positive cells." (PMID 36982993, 2023). "The molecular surface markers CD44 and ESA were assessed to identify whether the cells were tumor stem cells." (PMID 37408388, 2023). "Additionally, the intensities of Ki67 and CD44 staining, enhanced by ACTN1 upregulation, were markedly reduced by MYH9 downregulation in xenograft tumor tissues." (PMID 38057867, 2023). "Moreover, the effector memory T cells (TEM, CD44+CD62L-) (~91%) in TME increased significantly in Nano-CD & αPD-1 group, which is essential for preventing tumor recurrence via recognition of “old antigens”." (PMID 36774382, 2023). "In summary, CD44 shows tumour-inducing features, upregulation in PDAC compared to non-neoplastic pancreatic parenchyma, as well as negative prognostic impact and features consistent with drug resistance." (PMID 37108193, 2023). "Our results suggest that CD44 is a positive regulator of PD-L1 in BLCA and may be a key regulator of tumor macrophages infiltration and may be involved in M2 macrophage polarization." (PMID 37316699, 2023). "Our previous study found that GSCs from tumor tissues in the periphery of HI-type GBMs, presenting a high P/C ratio of CD44, expressed higher CD44 in stem-like cells and much higher invasion than GSC from GBM with a low P/C ratio of CD44 expression." (PMID 37760811, 2023). "Upon blocking CD44 from the TNBC cells, tumor growth is inhibited, suggesting that this feedback mechanism could provide a therapeutic target in the future." (PMID 36768435, 2023). "As we identified ADAM10 as a key protease to induce CD44 dependent transcriptional upregulation of MMP14 and MMP2, inhibition of CD44 cleavage by ADAM10 might be a future translational approach to prevent tumor cell migration and invasion." (PMID 36876041, 2023). "Furthermore, the combination treatment significantly increased the central memory phenotype of CD8+ T cells (TCM, CD44+ CD62L+; p < 0.01) in the spleens of tumor-bearing mice." (PMID 36949064, 2023). "Furthermore, the inhibition of NRF2 in ALDH+ OC cells and CD44+ BC cells has demonstrated a reduction in CSC properties, including chemoresistance, tumor growth, and spheroid formation." (PMID 37445860, 2023).